SMAD4 (SMAD family member 4)
Diseases named in the same sentence as SMAD4 in open-access papers (continued):
Sharing a sentence is not in itself a finding about the gene and the disease.
pancreatic cancer (continued). "We first analyzed by RPPA a series of signalling pathways in pancreatic cancer cells, expressing or not expressing SMAD4, and repeatedly stimulated with EGF “in vitro” in order to simulate “in vivo” conditions." (PMID 27655713, 2016). "Over-expression of Smad4 induces the expression of p21waf1 in breast cancer cells in the presence or absence of TGF-β stimulation, and Smad4 can bypass the TGF-β receptor activation to increase p21waf1 levels in pancreatic cancer cells." (PMID 27595937, 2016). "DPC4 (Smad4), a tumor suppressor gene, exhibits frequent mutations accompanied by LOH in approximately 20 % of pancreatic cancers, but no mutations have been reported in gastric cancers." (PMID 26207151, 2015). "On the other hand, a literature-based meta-analysis of biomarkers in operated pancreatic cancer did not support the prognostic value of SMAD4 in surgically resectable disease." (PMID 24465802, 2014). "We hypothesized a correlation between TGF-βR2/SMAD4 expression in the tumor, plasma TGF-β1 ligand level, genetic variation in TGF-B pathway and prognosis of pancreatic cancer." (PMID 24465802, 2014). "For example, when αvβ6 was blocked with antibodies in the early stages of disease in a transgenic pancreatic cancer mouse model, this accelerated cancer progression when SMAD4 was functional, but not in SMAD4-null animals." (PMID 24023846, 2013). "Thus, our study further confirmed that Smad4 and p16 played important role in the process of LNM in pancreatic cancer." (PMID 22860091, 2012). "The analysis showed that the high cytoplasmic expression levels of RhoT1, Smad4 and p16 in pancreatic cancer tissues had significantly negative correlation with lymph node metastasis (LNM) (P = 0.017, P = 0.032, P = 0.042, respectively)." (PMID 22860091, 2012). "Therefore, we have carried out this study to examine the expression of RhoT1, Smad4 and p16 in pancreatic cancer, and to analyze whether the expression patterns of RhoT1, Smad4 and p16 are correlated with metastatic potential and are predictive of clinical outcome in patients with pancreatic cancer." (PMID 22860091, 2012). "Also, there are relatively few studies that have examined the possible role of Smad4 and p16 in the progression of LNM and PNI in pancreatic cancer." (PMID 22860091, 2012). "SMAD4-dependence is supported by the fact that TGFβ cannot induce EMT in the pancreatic cancer cell lines IMIM PC-2 or CAPAN-1, which do not express functional SMAD4." (PMID 24281218, 2010). "Smad4 was reintroduced into the BxPC3 and Capan1 pancreatic carcinoma cell lines via retroviral transduction, and led to approximately 3- to 5-fold Smad4 overexpression (data not shown)." (PMID 17997817, 2007). "Smad4-dependent regulation of these secreted Smad4 targets is not restricted to cervical carcinoma cells and was confirmed in pancreatic carcinoma cells reexpressing Smad4 after retroviral transduction and in a stable Smad4 knockdown model." (PMID 17997817, 2007). "We demonstrate LINC00909 inhibits SMAD4 expression at the post-transcriptional level, which up-regulates the expression of pluripotency factors and activates the MAPK/JNK signaling pathway, leading to enrichment of cancer stem cells and cancer metastasis in pancreatic cancer." (PMID 38504385, 2024).
pancreatic cancer (continued). "Several studies have shown that the expression of RHOT1 is significantly increased in pancreatic cancer patients; siRNA-RHOT1 significantly inhibits the migration and invasion of SW1990 pancreatic cancer cells, with the mechanism mainly involving the regulation of SMAD4 expression." (PMID 38378644, 2024). "In addition to SMAD4/DPC4, other SMAD family proteins also have an effect on pancreatic cancer." (PMID 37685308, 2023). "SMAD4/DPC4 deletions occur late in the transformation of pancreatic intraepithelial neoplasia to pancreatic cancer, with heterozygous deletions occurring in nearly 60% of human pancreatic cancers and approximately 50% exhibiting homozygous deletions or intragenic inactivating mutations." (PMID 37685308, 2023). "In line with our data, preliminary clinical and molecular data from the Know Your Tumor (KYT) pancreas cancer program, which enables multiomic testing for DAC patients, suggests that low expression of SMAD4 and its target genes may contribute to FOLFIRINOX resistance." (PMID 37568581, 2023). "It has been reported that TGF-β1 signaling could be activated through noncanonical pathways in the Smad4-null pancreatic cancer cell line BxPC-3." (PMID 34862460, 2022). "However, our results suggested that SMAD4 alteration was not related to the overall survival of pancreatic cancer." (PMID 32950968, 2020). "However, there was no different clinical overall survival between pancreatic cancer patients with or without SMAD4 alterations." (PMID 32950968, 2020). "However, in pancreatic cancer, there was no obvious relationship observed between SMAD4 levels and clinical parameters." (PMID 28199217, 2017). "The aim of the present study was to improve our understanding of the way in which EGF governs the pancreatic cancer cell response to relevant stromal derived molecules, TGFβ1 and S100A8/A9, while also investigating whether SMAD4 participates in this complex scenario." (PMID 27655713, 2016). "A previous study of palbociclib in KRAS mutant pancreatic cancer cell lines showed concern that though palbociclib monotherapy inhibited cell proliferation, it appeared to also increase epithelial mesenchymal transition (EMT) in cell lines with wild-type SMAD4." (PMID 27167191, 2016). "Through such Smad-independent pathways a loss of Rac1b may allow for enhanced migration and invasion under the influence of TGF-β1 even in Smad4-negative pancreatic tumours." (PMID 24378395, 2014). "However, in pancreatic cancer, no obvious relationship was found between Smad4 staining and clinical parameters." (PMID 25333693, 2014). "Finally, loss of nuclear or loss of both nuclear and cytoplasmic expression of mothers against decapentaplegic homolog 4 (SMAD4), but also positive nuclear SMAD4 staining, has been reported to be of potential value to distinguish mainly pancreatic cancer from non-GI cancers." (PMID 37349623, 2024).
pancreatic cancer (continued). "Moreover, our finding that p38MAPK activity, but not Smad4, is required for HoCC indicates that targeting of this phenomenon may be applied in all pancreatic cancers and not only in the barely half of patient with unmutated Smad4/DPC4 gene." (PMID 22821859, 2012). "Pancreatic tumors were detected within 3 weeks following implantation of 104 parental control, STAT3 knockout (KO), SMAD4 KO, or TGFBR2 KO PDAC cells, and there was no statistical difference in tumor latency between the groups." (PMID 38573819, 2024). "In summary, due to the lack of SMAD4/DPC4 in most PDACs, the development of drugs that can function as an alternative to SAMD4 has become a popular target for pancreatic cancer therapy." (PMID 37685308, 2023). "A study in patients with advanced pancreatic cancer did not detect survival benefit with the addition of HCQ to gemcitabine and nab‐paclitaxel, however, a dedicated subgroup analysis to SMAD4 has not been performed." (PMID 34002944, 2021). "In the absence of SMAD4, KLF5 cooperates with SOX4 to promote tumor progression in pancreatic cancer cells." (PMID 31822964, 2020). "Smad4 target genes previously identified in colorectal and pancreatic carcinoma cells, namely E-cadherin, laminin-5, VEGF and thrombospondin-1, were not affected through Smad4 reexpression in C4-II cervical cancer cells (data not shown)." (PMID 17997817, 2007). "Target genes involved in the Smad4-mediated tumour suppression in colorectal and in pancreatic carcinoma cells, such as E-cadherin, laminin-5, VEGF and thrombospondin-1, however, did not respond to Smad4-reexpression in C4-II cervical cancer cells." (PMID 17997817, 2007). "Studies were selected using the following search terms (non-exhaustive list): “pancreas”, “pancreatic cancer”, “ pancreatic ductal adenocarcinoma”, “PDAC”, “TGF-beta”, “SMAD4”, “epithelial-mesenchymal transition”, “EMT”, “hybrid EMT”, “partial EMT” and/or “epithelial-mesenchymal plasticity”." (PMID 35205719, 2022). "Furthermore, the overexpression of ITGA2 could significantly inhibit the mRNA level of SMAD2 in pancreatic cancer cells, but not those of the SMAD3 or SMAD4." (PMID 35193647, 2022).
colorectal cancer (278 papers, 1998 to 2026). A primary or metastatic malignant neoplasm that affects the colon or rectum. "SMAD4 deficiency promotes colorectal cancer progression activating aerobic glycolysis through the upregulation of GLUT1 expression." (PMID 40139191, 2025). "Although Ctnnb1 mutations are uncommon in human colon cancer, Smad4 mutations are associated with poor-prognosis, recurrence and resistance to treatment in colorectal cancer patients and found mutated in 13% of CACs4." (PMID 40386410, 2025). "Here, we report two unrelated Italian families harboring two different SMAD4 intronic variants, c.424+5G>A and c.425-9A>G, which are clinically associated with colorectal cancer and/or juvenile GI polyps." (PMID 39063183, 2024). "Smad4 is often deleted in pancreatic and colorectal cancers, and loss of Smad4 was thought to severely compromise Smad signaling." (PMID 38569937, 2024). "SMAD4 deficiency promotes the progression of colorectal cancer by attracting tumor-associated neutrophils through the CXCL1/8-CXCR2 axis." (PMID 39100676, 2024). "Increased expression of TRIM33 in colorectal cancer is associated with the loss of Smad4 and indicates a poor prognosis in patients with colorectal cancer." (PMID 39389957, 2024). "Colorectal cancer progression is promoted by SMAD4 deficiency, which leads to the accumulation of MDSCs through the CCL15-CCR1 chemokine axis." (PMID 39100676, 2024). "Mutation or inactivation of SMAD4 promotes tumor metastasis, recurrence, or drug resistance, including in colorectal cancer, pancreatic ductal carcinoma, and lung cancer." (PMID 37035326, 2023). "The SMAD4 gene plays a very important role in the development of colorectal cancer, and the loss of this gene increases the likelihood of progression to the metastatic form of this cancer." (PMID 37237640, 2023). "The SMAD4 gene is mutated in about 13% of appendiceal cancers, which is close to that found in colorectal cancers (15%) and small bowel tumors (17.4%), but higher than in gastric cancers (5.2%)." (PMID 37509254, 2023). "Another study showed that KLF5 knockdown in SMAD4-deficient colorectal cancer cells increases TGFβ-induced apoptosis and makes the cells more sensitive to 5-fluorouracil treatment." (PMID 37377893, 2023). "In colorectal cancer, resistance to 5-FU-based therapy is influenced by SMAD4 gene expression, as patients with decreased SMAD4 gene expression probably have a higher risk of developing 5-FU-induced resistance." (PMID 37237640, 2023). "A common cytogenetic alteration observed in the development of colorectal cancer is the loss of genetic material in the region of the long arm of chromosome 18, where the SMAD4, SMAD2 genes and other tumor suppressor genes are located." (PMID 37237640, 2023). "SMAD4 loss is also associated with chemoresistance to 5-fluorouracil (5-FU), used in the treatment of colorectal cancer." (PMID 37237640, 2023). "We previously established a novel murine model of colitis-associated colorectal cancer (CAC) through a T cell lineage-restricted deletion of the Smad4 gene in mice." (PMID 36045676, 2022). "In patients with colorectal cancer treated with 5-FU, those with SMAD4 loss displayed a significant decrease in both overall survival and progression free survival." (PMID 35685436, 2022). "In the present study, we investigated a SMAD4 loss-of-function mutation, which is associated with chemoresistance and decreased overall survival in colorectal cancer (CRC)." (PMID 35805024, 2022).
colorectal cancer (continued). "Mutations and deletions of SMAD4 have been most commonly documented in pancreatic adenocarcinoma and biliary tract cancer and colorectal cancer." (PMID 36088360, 2022). "Fifteen genes were implicated and three tested for modulation by SMAD4 in patient‐derived colorectal cancer tumoroids." (PMID 34114372, 2022). "Regarding mutation (deletion) of SMAD4, colorectal cancer and pancreatic ductal carcinoma are associated with resistance to radiotherapy." (PMID 36088360, 2022). "Another study reported that the loss of expression of SMAD4-induced RICTOR/AKT signaling activation was correlated with the poor survival of patients with colorectal carcinoma." (PMID 36142267, 2022). "Mutation of TGF-β receptor type 2 (TGFBR2) leads to the microsatellite instability causing colorectal cancer, and also the loss of function of SMAD4 in the TGF-β signaling pathway promotes the tumor progression and poor survival in colorectal cancer." (PMID 33597969, 2021). "Mutations of R361H were seen only in one serrated polyp, while R361H in the MH2 domain is reported as the most common mutation of the SMAD4 gene in colorectal cancer." (PMID 35154600, 2021). "SMAD4 is the subject of inactivating mutations in some cancers, and loss of SMAD4 expression is a notable feature of most human cancers, including colorectal cancer (CRC)." (PMID 35154600, 2021). "Approximately 5.0–24.2% of colorectal cancers (CRCs) have inactivating mutations in SMAD4, making it one of the frequently mutated genes in CRC." (PMID 34301194, 2021). "KRAS mutations, BRAF mutations and SMAD4 mutations are less frequent in CSM2 colorectal cancers than in other subtypes." (PMID 34577783, 2021). "Loss of Smad4 in colorectal cancer enhanced chemoresistance to 5‐fluorouracil via activating AKT pathway." (PMID 33372356, 2021). "Nevertheless, previous studies have established some associations between SMAD4 mutation and protein expression with the survival of patients and progress of colorectal cancer." (PMID 35154600, 2021). "Patients who meet colorectal cancer screening criteria, and patients with SMAD4 mutations, should undergo colonoscopy." (PMID 34682843, 2021). "A recent study suggests that TRAIL produced from SMAD4-deficient colorectal cancer cells induces BMP2 in fibroblasts, which enhances invasiveness and metastasis of colorectal cancer." (PMID 33810241, 2021). "Smad4 mutations are found in approximately 50% of pancreatic adenocarcinomas, 20% of colorectal cancers and 5% of head and neck squamous cell carcinomas." (PMID 34760883, 2021). "Up-regulation of TRIM47 in colorectal cancers was associated with SMAD4 degradation, enhancing growth and invasion of colorectal cancer cells." (PMID 32226386, 2020). "Despite some reports pointing to an absence of acquired mutations, insertions, or microdeletions in Smad3 in the skin and parathyroid tumors, its somatic mutation associated with Smad2 and Smad4 mutations is a cause of sporadic colorectal carcinoma." (PMID 32508821, 2020). "Loss of SMAD4 expression is observed in 48% of human colitis-associated carcinoma samples as compared with 19% of sporadic colorectal carcinomas." (PMID 33348563, 2020). "At the same time, increased TIF1γ expression was correlated with a loss of Smad4 in colorectal cancer and predicted a poor prognosis for colorectal cancer patients." (PMID 31632911, 2019). "When SMAD4 expression is lost in colorectal cancers (CRCs), it is associated with advanced stage disease, the presence of lymph node metastasis, and poor prognosis." (PMID 31867281, 2019). "The SMAD4 tumor suppressor gene product inhibits transforming growth factor-β-mediated signaling and is mutated in ~10% of colorectal carcinomas." (PMID 30730996, 2019).